GSK3B (glycogen synthase kinase 3 beta)
Diseases named in the same sentence as GSK3B in open-access papers (continued):
Sharing a sentence is not in itself a finding about the gene and the disease.
Alzheimer disease (continued). "In humans, GSK3β is a regulatory kinase for over 40 different proteins in a variety of pathways, and has been implicated in a number of diseases including: Type II diabetes (Diabetes mellitus type 2), Alzheimer's Disease, inflammation, cancer, and bipolar disorder." (PMID 26942720, 2016). "Notably, overexpression of Gsk3b in the murine hippocampus causes dramatic alterations in both the dendritic tree morphology and the postsynaptic densities of newborn neurons and has been proposed as a target for the treatment of Alzheimer's disease." (PMID 24568636, 2014). "Together, our computational pipeline highlights PEP8 and PEP44 as promising κ-casein-derived inhibitors of GSK-3β, illustrating a rational design of food-derived peptides as potential multifunctional candidates for Alzheimer's disease." (PMID 41803220, 2026). "LiG‐AuNPs show potential for treating GSK‐3β‐related conditions like mood disorders, Alzheimer's disease, and viral infections through prolonged, targeted administration." (PMID 41020548, 2026). "This nanoparticle‐based lithium delivery method offers a promising therapeutic approach for brain disorders dependent on GSK‐3β activation, including mood disorders, tauopathies, and Alzheimer's disease." (PMID 41020548, 2026). "GSK-3β is an important therapeutic target in Alzheimer's disease due to its central role in tau hyperphosphorylation, and synaptic dysfunction." (PMID 41803220, 2026). "This aspect prompted us to evaluate a possible therapeutic application of the LiG‐AuNPs in the context of GSK‐3β‐dependent neurodegenerative illness, such as Alzheimer's disease." (PMID 41020548, 2026). "The activation of glycogen synthase kinase 3β (GSK‐3β) and the deterioration of spatial memory represent prominent pathological and clinical manifestations of Alzheimer's disease (AD)." (PMID 40418513, 2025). "Fucoxanthin and rosemarinic acid are able to prevent Alzheimer’s disease by stimulating the Nrf2-mediated antioxidant system through Akt/GSK-3β/Fyn pathway." (PMID 41198656, 2025). "Recent work by further clarified the role of endogenous H2S in Alzheimer's disease by demonstrating that CSE-dependent sulfide production leads to the persulfidation of glycogen synthase kinase 3β (GSK3β), a key regulator of tau phosphorylation." (PMID 40998690, 2025). "Consistent with the studies herein, GSK3β inhibition attenuates inflammation in preclinical disease models, including models of Alzheimer’s disease, psoriasis, and cardiomyopathy." (PMID 39880090, 2025). "In vitro studies have demonstrated the ability of GSK3β to phosphorylate over 40 residues of tau, most of which are present in tauopathies such as Alzheimer’s disease and CTE, including Thr231, Ser202 and Ser205." (PMID 40349043, 2025). "Ginsenoside Rg1 regulates cell apoptosis and improves Alzheimer’s disease via the Wnt/GSK-3β/β-catenin signaling pathway." (PMID 40417210, 2025). "CRMP2 serves as a physiological target for the kinases glycogen synthase kinase-3β (GSK-3β) and cyclin-dependent kinase 5 (Cdk5), both of which show heightened activity in Alzheimer’s disease." (PMID 40358171, 2025). "Activated Akt inhibits pro-apoptotic factors such as Bad and glycogen synthase kinase 3 beta (GSK‐3β), which is implicated in tau hyperphosphorylation, a hallmark of Alzheimer’s disease (AD)." (PMID 40964464, 2025). "In the present study, our objective was to screen a natural compound-based library specifically targeting GSK3β, a protein that plays a central role in neurodegenerative diseases such as Alzheimer’s disease AD and PD." (PMID 40573222, 2025). "This review focuses on the pivotal role of GSK3β in regulating autophagy and the resulting implications for neurodegenerative diseases, including Alzheimer’s disease, Parkinson’s disease, Huntington’s disease and ALS." (PMID 41190025, 2025).
Alzheimer disease (continued). "Disruptions in insulin signaling that regulate the GSK-3β pathway in diabetes, combined with hyperglycemia, may trigger tau phosphorylation and subsequent cleavage, which increases the risk of cognitive disorders, such as Alzheimer’s disease, in diabetic patients." (PMID 40909136, 2025). "Despite these hurdles, the potential to achieve robust, disease-modifying efficacy justifies the increased effort and underscores the promise of dual GSK3β/SIRT1 targeting strategies in Alzheimer’s disease." (PMID 41031163, 2025). "GYY4137 exhibits neuroprotective effects in Alzheimer's disease models by promoting the sulfhydration of glycogen synthase kinase 3β (GSK3β), thereby inhibiting tau hyperphosphorylation, a critical step in neurofibrillary tangle formation." (PMID 40998690, 2025). "Alzheimer's disease (AD) features progressive memory decline, Aβ plaque deposition, tau hyperphosphorylation (via GSK-3β activation), and impaired insulin signaling." (PMID 40948863, 2025). "In particular, dysregulation of GSK3β, a serine-threonine kinase that co-localizes with pSer129 α-Syn, has been described in PD and Alzheimer’s disease." (PMID 40988055, 2025). "GSK3β inhibition boosts autophagy and promotes toxic protein aggregate clearance, potentially mitigating Alzheimer’s disease and Parkinson’s disease progression." (PMID 41190025, 2025). "In fact, human PRNP transcription is decreased during normal aging and in some neuropathological contexts where GSK3β activity is upregulated, such as advanced Alzheimer’s disease (AD)." (PMID 40580266, 2025). "Neuroinflammation is a key pathological feature of Alzheimer’s disease, and pro-inflammatory cytokines are known to promote hyperphosphorylation of tau, partly through upregulation of tau-kinases such as GSK-3β." (PMID 41465235, 2025). "Other techniques include covalent and allosteric modulation of several molecules involved in Alzheimer’s disease (AD) pathogenesis, such as gamma-secretase and glycogen synthase kinase 3 beta (GSK-3β)." (PMID 41007636, 2025). "Origin, classification, and pharmacological effects of phytochemicals as GSK‐3β inhibitors in the treatment of Alzheimer's disease." (PMID 39129397, 2024). "In the context of Alzheimer’s disease (AD), GSK3-β has drawn extensive attention due to its involvement in the phosphorylation of tau protein, a key player in the development of neurofibrillary tangles, one of the hallmark pathological features of AD2." (PMID 38191548, 2024). "GSK3β and cdk5 are two major tau kinases whose activity is increased and prolonged in Alzheimer’s disease, however, it is also known that cdk5 is a negative regulator of GSK3β and inhibits its activity by increasing its phosphorylation on serine-9." (PMID 39520508, 2024). "Docking on GSK-3β was performed based on reported inhibitors that showed activity against many diseases, such as cancer, Alzheimer’s disease, and chronic inflammatory diseases." (PMID 39204199, 2024). "GSK-3β, IKK-β, and ROCK-1 kinases are implicated in the pathomechanism of Alzheimer’s disease due to their involvement in the misfolding and accumulation of amyloid β (Aβ) and tau proteins, as well as inflammatory processes." (PMID 38893493, 2024). "GSK-3β activity is increased in Alzheimer's disease brain, and blocking its activity has had ameliorating effects in AD mouse models." (PMID 38278659, 2024). "A study of GSK3β in Alzheimer’s disease found that acetylation of GSK3β at residue K15 (the equivalent of TgGSK K13) led to the over-activation of the kinase, which led to the promotion of tau hyperphosphorylation and an increase in disease phenotypes." (PMID 39386585, 2024). "In the pathogenesis of Alzheimer’s disease, theoverexpressionof glycogen synthase kinase-3β (GSK-3β) stands out dueto its multifaced nature, as it contributes to the promotion of amyloidβ and tau protein accumulation, as well as neuroinflammatoryprocesses." (PMID 39158934, 2024).
Alzheimer disease (continued). "Here, we show that the serine/threonine kinase GSK3β catalyzes the aggregation of the protein tau into Alzheimer’s disease (AD)-like filaments." (PMID 39693350, 2024). "In Alzheimer’s Disease, GSK3β plays a major role in phosphorylating Tau, which is thought to contribute to Tau aggregation." (PMID 37163077, 2024). "Co-targeting GSK3β and BChE in Alzheimer’s disease helps to modify disease progression and enhance cognitive function by addressing both tau pathology and cholinergic deficits." (PMID 39204336, 2024). "Glucocorticoid receptor modulation and neuronal calcium channel and glycogen synthase kinase-3 beta (GSK-3 beta) modulation targeting Alzheimer’s disease have also been reported for ethanoanthracene derivatives." (PMID 39204139, 2024). "Another study described that EGCG disrupts amyloid-beta aggregation in Alzheimer’s disease, enhances protective α-helix structures, and modulates critical neuronal pathways such as GSK3-β and PI3K/Akt to reduce oxidative stress." (PMID 39203859, 2024). "Glycogen synthase kinase-3β (GSK-3β), an isoform of GSK-3β, is well-documented for its role in the pathological processes of Alzheimer’s disease (AD)." (PMID 39598743, 2024). "Our research emphasizes Gas-miR36-5p as a novel G. elata-specific miRNA with neuroprotective properties in Alzheimer’s disease by targeting GSK-3β." (PMID 38139125, 2023). "AChE, NMDAR, β-secretase, Aβ oligomers, Aβ plaques, GSK-3β, neurofibrillary tangles, Ca2+ ions, and reactive oxygen species are elements involved in the pathogenesis of Alzheimer’s disease (AD) and represent significant potential targets for treatment." (PMID 38125832, 2023). "In conclusion, the third-generation cephalosporins are reported herein as GSK3β covalent inhibitors, offering insight into the mechanism behind their benefits in cancer and Alzheimer's disease." (PMID 37057264, 2023). "By utilizing existing clinical date from DisGeNET and undergoing protein-protein network analysis on cholesterol metabolism and Alzheimer’s disease, the top target genes selected were GSK3B, BACE1, SREBP2, CYP46A1, ABCA1, and TREM2." (PMID 37444065, 2023). "Due to GSK3B’s role in two separate pathways involving cell proliferation, as well as its direct effect on tau phosphorylation and amyloid-beta production, developments have been made to target GSK3B for the treatment of Alzheimer’s disease." (PMID 37444065, 2023). "Recent studies have reported the beneficial effects of cephalosporin antibiotics in cancer and Alzheimer's disease, implying potential inhibition of GSK3β." (PMID 37057264, 2023). "Late-stage functionalizations of enantioenriched piperazinederivatives were demonstrated, including synthesis of a drug compoundwith glycogen synthase kinase (GSK)-3β inhibitor activity withpotential for treating Alzheimer’s disease." (PMID 36735675, 2023). "Ten years later, 3APs were studied as inhibitors of GSK-3β, a serine/threonine kinase that plays critical roles in multiple cellular functions in the central nervous system and is considered a key player in Alzheimer’s disease (AD) pathophysiology." (PMID 37175540, 2023). "Two isoforms, GSK3α and GSK3β, have been identified and both are ubiquitously expressed in the brain and GSK3β is increased in the post-mortem brain of Alzheimer’s disease patients." (PMID 37754222, 2023). "This intricate interplay among PS1, GSK-3β, and their impact on Aβ metabolism and synaptic function contributes significantly to the pathogenesis of Alzheimer’s disease." (PMID 37781096, 2023). "Specifically, dysregulation of GSK-3β activity has been reported in neurological diseases such as bipolar disorder (BD) and in neurodegenerative disorders such as Alzheimer’s disease (AD), Parkinson’s disease (PD) and Huntington’s disease (HD)." (PMID 37108703, 2023). "Tideglusib (NP-12, NP031112) is a selective and irreversible GSK3β inhibitor that was previously in clinical trials for Alzheimer’s disease and progressive supranuclear palsy." (PMID 37762417, 2023).
Alzheimer disease (continued). "Dysfunction of GSK3β is involved in the pathogenesis of several psychoneuroses; therefore, GSK3β has been considered a therapeutic target for Alzheimer’s disease and bipolar disorder." (PMID 36949769, 2023). "It has been proposed that glycogen synthase kinase 3β (GSK3β) is involved in the hyperphosphorylation of tau in Alzheimer’s disease." (PMID 37754222, 2023). "A clinical casein kinase 2 inhibitor, CX-4945 (silmitasertib),shows significant affinity toward the DYRK1A and GSK3β kinases,involved in down syndrome phenotypes, Alzheimer’s disease,circadian clock regulation, and diabetes." (PMID 36883902, 2023). "In cancer, GSK-3β is often inactivated to allow for Wnt pathway activation, while in Alzheimer’s disease, GSK-3β is overly active, leading to increased tau phosphorylation and aggregation." (PMID 38002524, 2023). "To summarize, in subjects with Alzheimer’s disease, caffeic acid decreases oxidative stress and improves cognitive functions, probably by inhibiting NF-κB and GSK3β signaling and acetylcholinesterase and butyrylcholinesterase activity." (PMID 36614030, 2022). "In recent years, many Keap1–Nrf2 PPI inhibitors and GSK3β inhibitors have been reported for various indications, such as Alzheimer’s disease, cancers, Parkinson’s disease, kidney diseases, Acetaminophen (APAP)–induced liver injury, and ferroptosis." (PMID 36678511, 2022). "Glycogen synthase kinase 3β (GSK-3β) catalyses the hyperphosphorylation of tau protein in the Alzheimer’s disease (AD) pathology." (PMID 35698879, 2022). "It has been reported that EPC transplantation mitigated the increases in the levels of hippocampal Tau phosphorylation and its upstream GSK-3β in an experimental model of Alzheimer’s disease." (PMID 36371197, 2022). "Glycogen synthase kinase 3β (GSK3β) is a core protein, with a relevant role in many neurodegenerative disorders including Alzheimer’s disease." (PMID 35281935, 2022). "The inhibition of glycogen synthase kinase 3β (GSK3β) activity through pharmacological intervention represents a promising approach for treating challenging neurodegenerative disorders like Alzheimer’s disease." (PMID 35455423, 2022). "Activation of GSK3β has been described in a variety of neurodegenerative diseases, also using in vitro and in vivo ALS models and several GSK3β inhibitors have been tested in clinical trials related to Alzheimer’s disease and ALS." (PMID 35268572, 2022). "This widespread activity has also led to identifying GSK-3β dysregulation as responsible for the development of many diseases, such as Alzheimer’s disease (AD), bipolar disorder, diabetes, cardiovascular diseases, and cancer." (PMID 35409221, 2022). "GSK-3β has been reported to be involved in the pathogenesis of Alzheimer’s disease (AD) by phosphorylating tau protein to develop into paired helical filaments, leading to AD patients’ degenerative neuritis." (PMID 35422816, 2022). "On the other hand, therapies aiming to activate Wnt signaling, including DKK-neutralizing antibodies or GSK3β kinase inhibitors, have been considered for treatment of diseases with reduced Wnt signaling such as Alzheimer’s disease." (PMID 33257473, 2021). "Increased activity of the GSK-3β enzyme is a factor that manifests itself in the development of numerous disease entities such as Alzheimer’s disease, schizophrenia, diabetes and cancers." (PMID 33920768, 2021). "Several methods have been used to design and synthesize a series of derivatives, aiming at simultaneously regulating neuronal calcium channels and GSK-3β to produce effective targets for the treatment of Alzheimer's disease." (PMID 34987593, 2021). "(For details on GSK3β-amyloid-tau positive feedback, please see our 2019 publication on a multi-loop model of Alzheimer’s disease)." (PMID 33921683, 2021).
Alzheimer disease (continued). "Findings from this study confirms the therapeutic efficacy of EPS on regulating Alzheimer's disease (AD) by regulating GSK3-β and total tau proteins phosphorylation, which helped to restore the cellular viability." (PMID 33820886, 2021). "ADAM17, BACE1, CAPN1, CDK5, EIF2AK3, GRIN2B, and GSK3B were enriched in the Alzheimer disease pathway (hsa05010)." (PMID 33807157, 2021). "Additionally, glycogen synthase kinase 3β (GSK3β), whose role in glucose homeostasis has been extensively studied, participates in many cellular processes, and its dysregulation has been implicated in a wide range of diseases, such as obesity, type 2 diabetes, Alzheimer disease, and cancer." (PMID 33504020, 2021). "In SH‐SY5Y and mouse primary cells, we have demonstrated that an increased phosphorylation of tau by kinase GSK3β, as occurs in Alzheimer disease, can modulate the levels and enzymatic activity of cholinergic AChE." (PMID 32955735, 2021). "GSK-3 exists in two isoforms, GSK-3α and GSK-3β, with the latter having extensive implications in neurodegenerative diseases such as Alzheimer’s disease and neuropsychiatric disorders such as schizophrenia." (PMID 34571919, 2021). "Few studies have investigated the GSK3β phosphorylation by mAChR ligands, however, this would be a pathway to try to target for the treatment of both Alzheimer's disease and schizophrenia." (PMID 33584282, 2020). "Increased activity of Akt is observed in Alzheimer's disease brain tissues, resulting in an increase in the phosphorylation of the downstream proteins GSK3β(Ser9) (inhibits activity), Tau(Ser214) and mTor(Ser2448)." (PMID 33584282, 2020). "GSK-3β inhibition presents a new method for reducing the formation of both neurofibrillary tangles and amyloid plaques, two of Alzheimer's disease's pathological hallmarks." (PMID 32655767, 2020). "Expression profile, haplotypes, and activity of GSK3β have been intensively studied in a broad range of psychiatric and neurological diseases, such as schizophrenia, Parkinson’s, and Alzheimer’s diseases, and in the context of mood disorders." (PMID 32188010, 2020). "VPA promoted neurogenesis and GSK-3β dependent neurite outgrowth in a mouse model of Alzheimer’s disease." (PMID 32806546, 2020). "STAT3 activation also negatively regulates another common target GSK3β of Alzheimer’s disease and T2DM." (PMID 33150068, 2020). "Alzheimer’s disease (AD) was one of the first diseases reported involving an alteration in the activity of the GSK-3β enzyme." (PMID 33013321, 2020). "GSK3β plays important roles in a variety of human disorders, including inflammation, Alzheimer’s disease, mood disorders, diabetes, and cancer." (PMID 33066035, 2020). "An Alzheimer’s disease (AD) mouse model based on GSK3β overexpression is characterized by severe brain inflammation, e.g., increased numbers of activated microglia and enhanced TNF, IFN-γ, MIP-1α, -3α, and CCL2 (but also IL-10) expression." (PMID 32231133, 2020). "Glycogen synthase kinase-3β (GSK-3β) is a potential target in the field of Alzheimer’s disease drug discovery." (PMID 33105671, 2020). "Several lines of evidence have shown that GSK3β contributes to the development of such prevalent diseases as diabetes, Alzheimer’s disease, as well as mood disorders." (PMID 32188010, 2020). "GSK-3β is famous to be involved in a number of human disorders, including diabetes, cancer, oxidative stress, and Alzheimer’s disease at all." (PMID 32351385, 2020). "Recent studies have also suggested a possible role of GSK3β in neurodegenerative diseases, such as Parkinson’s disease (PD) and Alzheimer’s disease (AD)." (PMID 32993098, 2020). "For instance, a previous study demonstrated that dual BACE-1/GSK-3β inhibitors act through the inhibition of the NQO1 enzyme in order to counteract the oxidative stress in Alzheimer's disease." (PMID 33087132, 2020).